POSTN (periostin)
Diseases named in the same sentence as POSTN in open-access papers (continued):
Sharing a sentence is not in itself a finding about the gene and the disease.
POSTN also shares sentences with these, for which no sentence is quoted: Allergy (9 papers); acute myocardial infarction (5); chronic periodontitis (5); polycystic kidney disease (5); lung disease (4); subarachnoid hemorrhage (4); clear cell renal cell carcinoma (3); diabetic retinopathy (3); glomerulopathies (3); hypertrophy (3); membranous nephropathy (3); renal failure (3); thymoma (3); adenocarcinoma (2); bullous pemphigoid (2); chronic rhinosinusitis with nasal polyps (2); chronic sinusitis (2); eczema (2); focal segmental glomerulosclerosis (2); kidney (2); multiple myeloma (2); myocardial ischemia (2); pancreas carcinomas (2); pemphigus vulgaris (2); rhinosinusitis (2); stenosis (2); -deficient (1); abdominal aortic aneurysm (1); acute bronchiolitis (1); acute rheumatic fever (1).
A further 98 diseases each share a sentence with POSTN in 1 paper.